SPP1 (secreted phosphoprotein 1)
Diseases named in the same sentence as SPP1 in open-access papers (continued):
Sharing a sentence is not in itself a finding about the gene and the disease.
Pneumocystis infection (1 paper, 2010). "Among the genes that were affected by dexamethasone and further affected by Pneumocystis infection, Mgst1 and Hspa1b genes were down-regulated, while Cd14, Irf8, Il1b, Cxcl13, Cxcr4, Fn1, Irf1, Cd74, S100a9, and Spp1 genes were up-regulated in all four groups." (PMID 20377877, 2010).
POEMS syndrome (1 paper, 2022). POEMS syndrome is a paraneoplastic syndrome characterized by polyradiculoneuropathy (P), organomegaly (O), endocrinopathy (E), clonal plasma cell disorder (M), and skin changes (S). "Of interest, while SPP1 expression was upregulated only in a part of POEMS clones, serum levels of osteopontin (OPN), encoded by SPP1, were significantly elevated in all patients with POEMS syndrome and well correlated with serum levels of VEGF." (PMID 36129760, 2022).
salivary gland neoplasm (1 paper, 2022). Tumors of the SALIVARY GLANDS. "The resulting candidate genes as possible therapeutic targets were FN1, SPP1, EGF, and ERBB2, and all those genes had been tested as a target in other neoplasm kinds but not salivary gland neoplasm." (PMID 36146635, 2022).
Salmonella Infections (1 paper, 2022). Infections with bacteria of the genus SALMONELLA. "The Salmonella infection could strongly enhance the expression Spp-1 and inhibit Salmonella reproduction." (PMID 36539715, 2022).
squamous intraepithelial lesion (1 paper, 2025). "Additionally, SPP1+ TAMs interact with cancer cells via the SPP1-CD44 signaling axis, an interaction that is more pronounced in high-grade squamous intraepithelial lesion (HSIL) and CC samples compared to low-grade squamous intraepithelial lesion (LSIL) samples." (PMID 41341850, 2025).
tauopathy (1 paper, 2023). Neurodegenerative disorders involving deposition of abnormal tau protein isoforms (tau proteins) in neurons and glial cells in the brain. "In contrast, MG2 and MG4, disease-associated cells induced by tauopathy, exhibit higher levels of proinflammatory genes like Apoe, Spp1, Nfkb1, and Akt3, as well as STAT3, IL-8, NF-kB, and JAK/STAT signaling." (PMID 37961627, 2023).
temporal lobe epilepsy (1 paper, 2025). A localization-related (focal) form of epilepsy characterized by recurrent seizures that arise from foci within the temporal lobe, most commonly from its mesial aspect. "It has also been reported that the Spp1 intercellular interaction pathway is significantly increased in mice with temporal lobe epilepsy." (PMID 40292254, 2025).
tenosynovial giant cell tumour (1 paper, 2023). "MMP9, SPP1, and TYROBP were identified as osteoclast-specific up-regulated genes of the tenosynovial giant cell tumour via bioinformatic analysis, which had a reasonable diagnostic efficiency and served as potential drug targets." (PMID 38017559, 2023).
Thoracic neoplasm (1 paper, 2023). "The SPP1 network contains several immune-related proteins as well as cancer-related proteins (e.g., Neoplasia of cells, CCND1, Thoracic neoplasm and Metastatic solid tumor)." (PMID 37513116, 2023).
Thyroid adenoma (1 paper, 2015). The presence of a adenoma of the thyroid gland. "Some thyroid adenomas have been found weakly SPP1 positive, whereas many carcinomas were strongly positive." (PMID 25887408, 2015).
uremia (1 paper, 2022). A clinical syndrome associated with the retention of renal waste products or uremic toxins in the blood. "Meanwhile, by verifying the expression of these hub genes in the uremia-induced VC group, we found that Sost, Ibsp, Fn1, and Spp1 were highly expressed in calcified samples, while Col1a1 was lowly expressed." (PMID 35313524, 2022). "We constructed ROC curves of each hub gene separately and found that their area under ROC curves of Sost, Ibsp, Fn1, Col1a1, and Spp1 were all close to one in the uremia-induced VC group in GSE146638, with the normal group as control." (PMID 35313524, 2022).
tumor (1,546 papers, 2004 to 2026). "Cell‒cell communication analysis shows that 'T-cell-dominant' ecotypes have higher MHC-I signalling pathways in tumour cells, whereas 'Desert' ecotypes have higher SPP1+ macrophage signalling, underlining the role of SPP1 on immune remodelling." (PMID 41636115, 2026). "SPP1 is closely associated with tumor-associated macrophages, and SPP1 + macrophages are associated with poor prognosis." (PMID 41056019, 2026). "SPP1+ tumor-associated macrophages (TAMs) are implicated in promoting tumor progression, angiogenesis, and immune evasion." (PMID 41639044, 2026). "We identified extensive cellular heterogeneity within the TME, dominated by CMS2/CMS3 epithelial states, SPP1+ tumor-associated macrophages, diverse T-cell subsets, and CXCR4+ B cells." (PMID 41683916, 2026). "This review describes the immunosuppressive effect of secreted phosphoprotein 1 (SPP1)+ tumor-associated macrophages (TAMs) in coordinating the tumor microenvironment (TME) as a functionally unique myeloid cell subgroup." (PMID 41751193, 2026). "SPP1+ macrophages constitute a functionally distinct and clinically significant subset of tumor-associated macrophages that contribute to cancer progression through multiple mechanisms." (PMID 41425545, 2025). "SPP1 is highly expressed across multiple cancers and is associated with tumor progression, poor prognosis, immune evasion, metastasis, drug resistance, and alterations in the tumor microenvironment." (PMID 41391064, 2025). "SPP1+ TAMs, located in the tumor core, co-localized with cancer-associated fibroblasts to promote tumor growth and further contributed to worse prognosis." (PMID 40230843, 2025). "The SPP1+ tumor-associated macrophages (TAMs) have been implicated in tumor metastasis and immune evasion." (PMID 40376263, 2025). "By interacting with tumor-associated cells such as fibroblasts and macrophages, SPP1 activates signaling pathways like PI3K/AKT and MAPK, promoting cell survival, migration, and invasion." (PMID 41391064, 2025). "Based on TCGA-LIHC cohort, we validated that the SPP1+ TAMs subset is associated with tumor progression and poor prognosis in HCC." (PMID 40230843, 2025). "SPP1+ tumor‐associated macrophages are emerging as key regulators of the tumor immune microenvironment and disease progression." (PMID 41031219, 2025). "Spatial and deconvolution analyses reveal that CXCL9+ TAMs preferentially localized to the tumor periphery, whereas SPP1+ TAMs accumulated in the tumor core and were associated with advanced disease stages and worse overall survival in multiple cohorts." (PMID 40725473, 2025). "Their clinical studies showed that elevated SPP1 levels in the TME are linked to tumor progression by suppressing CD8 + T cell proliferation and IFN-γ production." (PMID 41391064, 2025). "The findings revealed that SPP1 is not only highly expressed in tumor cells but also closely associated with immune cell infiltration and regulation of the TME." (PMID 41391064, 2025). "whereas SPP1+ macrophages are associated with promoting angiogenesis and facilitating tumor progression." (PMID 40191203, 2025). "Originally identified in cancer as tumor‐associated macrophages (TAMs), SPP1+ macrophages have since been implicated in various conditions, including aging, chronic inflammatory disorders, neurodegenerative diseases, and tissue remodeling." (PMID 40047497, 2025). "Single-cell and spatial transcriptomic analyses have revealed that SPP1 is highly expressed by a specific subset of SPP1+ tumor-associated macrophages." (PMID 41268553, 2025). "SPP1+ tumor-associated macrophages have been associated with CRC malignancy and liver metastasis, and SPP1 is a diagnostic and prognostic marker for CRC." (PMID 40092488, 2025). "We identified genes, such as SPP1, preferentially expressed in tumor-associated macrophages (TAMs) and noted the MITF regulatory network appeared active in the M2-like TAMs." (PMID 40894019, 2025).
tumor (continued). "In various cancers, tumor-associated macrophage (TAM) expressing SPP1 (TAM-SPP1) facilitated immune suppression and tumor progression by interacting with CD44 receptors on tumor cells." (PMID 39862439, 2025). "M2 macrophages, often referred to as tumor-associated macrophages (TAMs), show significantly greater expression of SPP1 than M1 macrophages do, which is consistent with previous findings." (PMID 41425595, 2025). "The hypomethylated and upregulated PRAME can also promote the recruitment of monocytes to tumor tissues and differentiation into tumor-associated macrophages (TAMs), including SPP1 macrophages." (PMID 40425545, 2025). "In the tumor microenvironment, each of these subsets express different molecular functions, including immunosuppression and promotion of angiogenesis, with SPP1+ TAMs being particularly associated with malignancy." (PMID 40034694, 2025). "Functional analyses suggested that tumor-associated macrophages (TAMs) secrete SPP1, which binds to CD44 on neoplastic-stemness cells, activating the PI3K/AKT pathway and driving lncRNA transcription to promote metastasis." (PMID 40076844, 2025). "Once within the TME, SPP1 exerts profound effects on tumor-associated macrophages (TAMs), particularly by promoting their M2-like polarization, a state characterized by immune suppression, tissue remodeling, and tumor-promoting functions." (PMID 41391064, 2025). "In contrast, immunosuppressive populations such as regulatory T cells (Tregs), M2-polarized macrophages, myeloid-derived suppressor cells (MDSCs), and SPP1+ tumor-associated macrophages (TAMs) support tumor immune evasion and are linked to poor prognosis." (PMID 41244711, 2025). "We analyzed the expression of SPP1 and its receptor-associated genes across the cell types in primary tumor, metastatic, and normal samples." (PMID 41268553, 2025). "Previous studies have linked C1qc+ TAMs to phagocytosis, antigen presentation, and anti-tumor immune response, while Spp1+ TAMs are often associated with immunosuppression." (PMID 40917508, 2025). "Mammary gland studies in ApcMin/+ mice showed increased ductal hyperplasia and overgrowth, along with elevated expression of ERα, ERRα, and SPP1—markers associated with estrogen signaling and tumor development." (PMID 41008589, 2025). "At the same time, tumor-associated SPP1+ Macrophage interact with most cells on the SPP1 signaling pathway." (PMID 40406147, 2025). "This synergistic effect also induces macrophage reprogramming from M2 protumor Spp1+ tumor-associated macrophages (TAMs) to Cd74+ TAMs, which act as antigen-presenting cells (APCs)." (PMID 40312419, 2025). "The interaction between SPP1 macrophages and tumor associated fibroflasts exert important functions such as determines the efficacy of immunotherapy, metastasis angiogenesis; immune suppression of cancer, CD8 T cell exhaustion." (PMID 41425545, 2025). "Encoded by SPP1, OPN reshapes the tumor immune microenvironment by inducing M2-like TAM polarization, suppressing dendritic cell migration, and promoting Th1 responses via IL-12 and TNF-α." (PMID 40895569, 2025). "Tumor regions expressing CDKN2A exhibit distinct infiltration of SPP1(+) tumor-associated macrophages (TAMs), MMP7 enrichment, and unique signaling interactions with adjacent regions." (PMID 40406488, 2025). "Re‐polarizing TAM away from Spp1‐associated phenotypes can re‐activate anti‐tumor immunity by fostering productive myeloid‐T cell communication, enabling immune rejection of tumors." (PMID 39639496, 2025). "Spatial profiling demonstrates that TREM2 or SPP1-labeled, AR-imprinted macrophages cluster near tumor nests, cancer-associated fibroblasts (CAFs), and vascular hubs." (PMID 41488638, 2025). "Effects on Tumor Cells: Elevated SPP1 levels are associated with radioresistance in esophageal cancer." (PMID 41391064, 2025).
tumor (continued). "Co-expression and interactions between SPP1+ tumor-associated macrophages (TAMs) and regulatory T cells (Tregs) have been identified within CD44-enriched regions in the TME." (PMID 41425545, 2025). "It is well known that SPP1 encodes osteopontin (OPN), a phosphorylated glycoprotein regarded as a key component for tumor cell evolution and microenvironment reprogramming." (PMID 40666097, 2025). "Cluster 1 expressed S100a4, S100a6, and Spp1, genes associated with tumor progression and metastasis." (PMID 41567211, 2025). "Their abundance within tumours is associated with shorter overall survival, mirroring findings in other malignancies where SPP1+ macrophages contribute to tumour aggressiveness." (PMID 40395129, 2025). "Box plots show increased expression levels of genes such as S100A1, C2, and SPP1, which are associated with tumor progression and metastasis." (PMID 41288989, 2025). "Due to its widespread involvement in tumor progression, SPP1 is increasingly recognized as a diagnostic and prognostic biomarker in cancer." (PMID 41391064, 2025). "In cancer, SPP1+ tumour‐associated macrophages contribute to tumour growth, angiogenesis, and immune evasion, often interacting with T cells and stromal components to sustain an immunosuppressive microenvironment." (PMID 40395129, 2025). "scRNA-seq sub-cluster analysis identified macrophages with immunosuppressive (M2-like) traits overexpressing TREM2 and SPP1, genes linked to tumor angiogenesis and ICB therapy." (PMID 41035074, 2025). "SPP1 protein was expressed in both pleomorphic tumour cells and tumour associated macrophages (TAMs) (see section 3)." (PMID 40790295, 2025). "Previous studies have shown that SPP1 expressing Tumor Associated Macrophages (TAMs) are primarily enriched in AFP positive HCC and are characterized by reduced phagocytic function but enhanced pro-angiogenic capacity, which aligns with our findings." (PMID 40474968, 2025). "In HNSCC, SPP1+ TAMs show functional coupling to tumor and stromal programs and are linked to invasive phenotypes, while antigen-presenting macrophages co-localize with T-cell aggregates and tertiary lymphoid features." (PMID 41487561, 2025). "In line with a recent report that CXCL9 and SPP1 indicate tumor-associated macrophage polarity in human cancers, Cxcl9 expression was significantly higher in Trem2− macrophages, whereas Spp1 expression was significantly upregulated in Trem2+ macrophages." (PMID 39838454, 2025). "Japanese researchers confirmed that cytotoxic T lymphocyte-associated antigen-4 (CTLA-4) is highly expressed in SPP1+ macrophages at the tumor invasion front, which are considered to be markers of exhaustion." (PMID 40191203, 2025). "Beyond their impact on tumour metabolism, SPP1+ TAMs have been shown to interact extensively with cancer‐associated fibroblasts (CAFs), a key process in tumour progression." (PMID 40395129, 2025). "ScRNA‐seq revealed an immunosuppressive TME enriched with regulatory T cells (Tregs), exhausted CD8+ T cells, and SPP1+ tumor‐associated macrophages (TAMs)." (PMID 41028931, 2025). "Unexpectedly, SPP1+ macrophages, previously implicated in tumor promotion, showed relatively stable proportions across disease stages, suggesting a more complex role." (PMID 41246350, 2025). "In parallel, monocytes and tumor-associated macrophages (TAMs) expressing markers such as Arg1, Spp1, and Il1b, are known to contribute immune suppression in PDAC and other malignancies." (PMID 40661354, 2025). "In liver metastases, TGF‐β and IL‐6 can deliver signaling to the liver and promote the enrichment of intermediate clusters associated with fibronectin and SPP1 expression, and induce tumor‐specific T cell exhaustion." (PMID 41176774, 2025). "Pro-inflammatory (TNFSF10+) and pro-tumor (SPP1+) subtypes were linked to distinct TME profiles, immunotherapy responses, and clinical outcomes." (PMID 40422244, 2025).
tumor (continued). "Evidence indicates that SPP1 promotes the skewing of macrophages toward the M2 phenotype, which is closely associated with anti-inflammatory responses, tissue remodeling, and tumor progression." (PMID 41391064, 2025). "Mφ-SPP1, which has been linked to angiogenesis and tumor progression, was further characterized by delineating its transcriptomic features." (PMID 40925909, 2025). "Secreted phosphoprotein 1 (SPP1), expressed by tumor-associated macrophages (TAMs), contributes to tumor progression and immune suppression, and its high expression correlates with poor prognosis in cancers." (PMID 41221295, 2025). "Genetic SPP1 deficiency in macrophages delays hypoxic adaptive tumor growth and enhances the tumor response to anti-programmed cell death-1 (anti-PD-1) therapy." (PMID 41425545, 2025). "Single‐cell analysis showed that CE2‐high areas were rich in SPP1‐positive tumor‐associated macrophages(TAM), basal‐like epithelial cells, and hypoxic cancer‐associated fibroblasts(CAF)." (PMID 40432877, 2025). "Secreted phosphosprotein 1 (SPP1)High tumor‐associated macrophages (TAM) are abundant tumor myeloid cells that are immunosuppressive, pro‐tumorigenic, and have a highly negative prognostic factor." (PMID 39639496, 2025). "Nonetheless, the process by which SPP1+ macrophages recruit tumor-associated neutrophils still require further research." (PMID 39920772, 2025). "Subclustering analysis of tumor‐associated macrophages (TAM) identified three distinct subtypes: SPP1+ TAM, M1 macrophages, and M2 macrophages." (PMID 40843133, 2025). "Accumulating research mentioned the key effect on the tumor transformation, especially the deficiency of SPP1 in mouse model, suggesting that the SPP1 knockdown can inhibit the transformation from MASLD to HCC." (PMID 38726780, 2025). "Although SPP1+ Mφ markers were not highly expressed in macrophages in GSE140228, they were overrepresented in SPP1+ tumor-associated macrophages (TAMs) in GSE156337." (PMID 39691723, 2024). "Recurrent cSCC trended to exhibit worse immunosuppressed microenvironment featured by T cell exclusion, CD8+ T cell exhaustion, and enrichment of pro-tumor SPP1+ tumor-associated macrophages (TAMs)." (PMID 39558960, 2024). "Mø-SPP1 presented as a typical protumor M2 Tumor-associated macrophages (TAMs) and preferentially enriched in metastatic sites (GBC-LI), consistent with previous studies." (PMID 38822440, 2024). "Other studies have found that SPP1 + TAMs can interact with tumor-associated fibroblasts and prevent lymphocytes from infiltrating the tumor core." (PMID 38365757, 2024). "Using single‐cell RNA sequencing (scRNA‐seq) data, it is founded that NAMPT is highly expressed in SPP1+ tumor‐associated macrophages (TAMs), a unique subset of TAMs associated with immunosuppressive activity." (PMID 38308188, 2024). "Regarding the input pathways in target cells, the receptors associated with C2 ALOX5+MCs were primarily CD99, SELE, and SPP1, while the receptors related to tumor cells included TWEAK, CEACAM, and CD96." (PMID 39224598, 2024). "The interplay between UPP1high tumor cells and SPP1+ macrophages was linked with a variety of chemokines, including CCL2_CCR2, CCL3_CCR5, CXCL3_CXCR2, and CXCL8_CXCR1, as well as interactions such as IL1B_IL1_receptor and TGFB1_TGFbeta_receptor1." (PMID 38331898, 2024). "An important immunosuppressive function in the GC metastatic microenvironment is the interaction between clusters of differentiated (CD) 8+ fatigued T lymphocytes and tumor-associated macrophages (TAMs) + secreted phosphoprotein 1 (SPP1)." (PMID 39338286, 2024). "SPP1+ macrophages can also interact with tumor-associated fibroblasts, epithelial cells, and malignant cells, promoting fibrosis, extracellular matrix restructuring, and the formation of an immune-suppressive tumor barrier." (PMID 39776914, 2024).